EGFR (epidermal growth factor receptor)
Diseases named in the same sentence as EGFR in open-access papers (continued):
Sharing a sentence is not in itself a finding about the gene and the disease.
lung cancer (continued). "Overexpression of EGFR was found in 50-70% of human lung cancer, and deregulated expression of EGFR together with ligand binding and concomitant receptor activation promotes tumor cell growth, proliferation, and survival." (PMID 25413624, 2014). "We provide evidence that downregulation of PDK4 is responsible for such metabolic rewiring, is sufficient to drive EMT, and promotes erlotinib resistance in EGFR mutant lung cancer cells." (PMID 25379179, 2014). "In our previous study, we showed that epidermal growth factor receptor (EGFR) inhibitor gefitinib and erlotinib both induced autophagy in lung cancer cells." (PMID 25327881, 2014). "Suppressing EGFR endocytos decreased cell viability and increased apoptotic cell death in gefitinib-insensitive lung cancer with wtEGFR in vitro and in vivo." (PMID 24658031, 2014). "Tumor-targeted therapies, such as anti-EGFR treatments for lung cancer and anti-HER2 treatments for breast cancer, are highly effective in disease management in biomarker-defined patient populations." (PMID 25379179, 2014). "Epidermal Growth Factor Receptor (EGFR) is one of the receptor tyrosine kinase associated to lipid-raft and is involved in lung cancer." (PMID 24625581, 2014). "Striking therapeutic advances in metastatic NSCLC have been observed with targeted agents using molecular selection, notable for patients with EGFR mutant or ALK-rearranged lung cancer." (PMID 25505733, 2014). "For lung cancer, factors, such as age, gender, stage, smoking history, Myc protein level, and EGFR/KRAS/ALK alteration status were included in the multivariate model." (PMID 25333947, 2014). "MiR-133a can inhibit cell invasiveness and cell growth through suppressing the expressions of IGF-1R, TGFBR1 and EGFR, which then influences the downstream signaling in lung cancer cell lines." (PMID 24816813, 2014). "Because S2RPGRMC1 associates with EGFR, we searched for downstream events regulated by this interaction and found that S2RPGRMC1 has a profound impact on protease activation in lung cancer cells." (PMID 25594057, 2014). "Although the treatment mechanism of celastrol has been reported in two NSCLC cell lines H1975 and A549, our results further indicated a new treatment mechanism of celastrol in a selective type of EGFR survival dependent gefitinb-resistant lung cancer." (PMID 24662070, 2014). "Presently, only EGFR mutated tumors are eligible to receive EGFR TKI, representing 10 % of all lung cancer patients." (PMID 25249545, 2014). "We provided direct evidence that A549 cells constitutively expressed EGFR and ErbB2, while the expression of EGFR increased after BTC stimulation in human lung cancer cells." (PMID 24629040, 2014). "In this study, we investigated the role of DDX3X in acquisition of EGFR-TKI resistance in lung cancer cells." (PMID 25343452, 2014). "Afatinib-induced tumour shrinkage was also observed in transgenic mice with inducible expression of the oncogenic EGFR L858R mutant in lung epithelium; within days, afatinib reduced lung cancer size by more than 80 % as assessed by imaging studies." (PMID 24643470, 2014). "In the current study, we provide the first evidence that IQGAP3 promotes lung cancer growth and metastasis by enhancing EGFR-mediated ERK signaling." (PMID 24849319, 2014). "We show that G724S mutant EGFR is oncogenic and that it differs from classic lung cancer derived EGFR mutants in that it is cetuximab responsive in vitro, yet relatively insensitive to small molecule kinase inhibitors." (PMID 24894453, 2014). "Tyrosine kinase inhibitors (TKI) targeting the epidermal growth factor receptor (EGFR) represent a promising new group of anticancer agents for the treatment of patients with non–small cell lung cancer (NSCLC)." (PMID 25103305, 2014). "CTC were detected in pretreatment blood samples from all 8 EGFR-mutant lung cancer patients studied." (PMID 24465542, 2014).
lung cancer (continued). "We investigated the effect of CK2 inhibition in lung cancer cells with T790M-mediated resistance to the EGFR-TK inhibitor." (PMID 25486409, 2014). "Overexpression of PDK4 partially blocked TGFβ-induced EMT; conversely, PDK4 inhibition via RNAi-mediated knockdown was sufficient to drive EMT and promoted erlotinib resistance in EGFR mutant lung cancer cells." (PMID 25379179, 2014). "In this study, we sought to investigate the role of DDX3X in conferring EGFR-TKI resistance in lung cancer cells." (PMID 25343452, 2014). "From January 2010 to March 2011, 357 patients managed at the Hotel-Dieu hospital for lung cancer had EGFR testing for clinical purpose." (PMID 24885034, 2014). "In line with this, we also confirmed the persistence of EGFR dependency in T790M-mutant, lung cancer cells." (PMID 25486409, 2014). "EGFR-TKI can inhibit lymphangiogenesis in EGFR mutant lung cancer while suppressing vessel diameter and expansion area." (PMID 25539607, 2014). "The efficacy of erlotinib in advanced non-small-cell lung cancer has been demonstrated in several trials, but only two cases of complete and prolonged response in wild-type epidermal growth factor receptor locally advanced lung cancer have been published." (PMID 24661457, 2014). "ADAM17 has been shown to shed ligands of EGFR, such as amphiregulin and TNFα, and subsequently activate EGFR, thereby improving the proliferation and migration of lung cancer cells." (PMID 25364437, 2014). "Multiplex assays and next-generation sequencing in lung cancer samples are tested for several genomic aberrations simultaneously and usually include EGFR genotyping." (PMID 25295228, 2014). "Epidermal Growth Factor Receptor (EGFR) targeting therapies are currently of great relevance for the treatment of lung cancer." (PMID 25227424, 2014). "The cell line A549 was chosen for this study not only because it has the lowest RBM5 expression in seven different lung cancer cell lines, but also because it has wild-type EGFR-positive expression and gene amplification, which are more common in NSCLC." (PMID 25441176, 2014). "Inhibitors of the epidermal growth factor receptor (EGFR) are a prototypic example and have produced consistently high response rates in a subgroup of patients with non–small-cell lung cancer (NSCLC) with activating EGFR mutations." (PMID 25594059, 2014). "Even epidermal growth factor receptor (EGFR) tyrosine kinase inhibitors are only effective in a small population of lung cancer patients." (PMID 25105957, 2014). "Taken together, our findings suggest a novel insight that EGFR endocytosis is a rational therapeutic target in lung cancer with wtEGFR, in which the combined efficacy with gefitinib is expected." (PMID 24658031, 2014). "Consistent with the proposed mechanistic model, Hsp90 function appears to be essential to maintain high-level expression of mutant EGFR in lung cancer cells." (PMID 25427151, 2014). "Whereas, in the cancers of esophagus, oral cavity, lung, and head and neck, miR-27a is downregulated, and miR-27a directly targets MET and EGFR and suppresses their expression in lung cancer." (PMID 25166914, 2014). "The 15 k custom microarray predicted multiple exon skipping in the 3′ region of HER1/EGFR in SRSF2-over-expressing H358 lung cancer cells, which was confirmed by quantitative RT-PCR." (PMID 24428911, 2014). "In the present study, we determined that Rab25 regulated EGFR endocytosis, and its expression status was significantly correlated with the response of gefitinib in lung cancer with wtEGFR." (PMID 24658031, 2014).
lung cancer (continued). "Gefitinib and erlotinib are small-molecule tyrosine kinase inhibitors (TKIs) that target EGFR, and such inhibitors were the first targeted drugs to enter clinical use for the treatment of lung cancer." (PMID 25202368, 2014). "The proapoptotic BH3-only protein Bim was essential for imatinib-induced apoptosis in KIT-dependent gastrointestinal stromal tumor cells and erlotinib-induced apoptosis in EGFR mutant lung cancer cells." (PMID 25431951, 2014). "The activated receptors such as VEGFR1, VEGFR2, and EGFR play very important roles in the migration and proliferation of cancer cells including lung cancer cells." (PMID 25138052, 2014). "Afatinib exhibits superior anticancer activity in lung cancer patients harboring gefitinib/erlotinib-resistant mutant EGFR (including T790M, exon 20 insertion, and T790M/L858R double mutation)." (PMID 25364578, 2014). "LBH589 has also been reported to inhibit angiogenesis and induce apoptosis, and delay of DNA damage repair in lung cancer cells with activated EGFR." (PMID 24418474, 2014). "TFC and TNC can effectively suppress the growth of lung cancer cells in vitro, ex vivo and in vivo by targeting EGFR/VEGFR-Akt/NF-κB pathways." (PMID 25138052, 2014). "In summary, autophagosome-mediated EGFR down-regulation induced by CX-4945, a potent and selective CK2 inhibitor, enhances the efficacy of EGFR-TKI on EGFR-mutant lung-cancer cells with resistance by T790M." (PMID 25486409, 2014). "Acquired resistance to EGFR-tyrosine kinase inhibitors TKIs is observed in lung cancer with cMET amplification and is considered the main escape route for EGFR-targeted therapies." (PMID 24638075, 2014). "In the treatment of lung cancer, recent years have seen a remarkable boom of targeted therapy, focused mainly on the EGFR inhibition with erlotinib and gefitinib, and neoangiogenesis inhibition with VEGF inhibitor bevacizumab." (PMID 24574864, 2014). "In nonsmall cell lung cancer, amplification of MET is associated with resistance to gefitinib, the reversible EGFR tyrosine kinase inhibitor, via ErbB3 activation." (PMID 24500024, 2014). "The most common mechanism of acquired resistance to erlotinib or gefitinib is emergence of the “gatekeeper” mutation in EGFR itself, which likely indicates the “addiction” of lung cancer to EGFR signaling." (PMID 24722523, 2014). "Immunohistochemical method and lymphatic endothelium specific antibody D2-40 were used in the experiment to observe the influence of EGFR-TKI on lymphangiogenesis in lung cancer." (PMID 25539607, 2014). "Here we present the retrospective analysis of a clinical validation study of the EGFR PCR test on a subset of lung cancer specimens from patients screened for the EURTAC trial." (PMID 24586842, 2014). "The distinguished profile of EGFR distribution between these two lung cancer cell lines was confirmed by fluorescence intensity plot analysis and in other lung cancer cell lines." (PMID 24658031, 2014). "Lung cancers harboring constitutively active mutant EGFR are exquisitely sensitive to EGFR tyrosine kinase inhibitors (TKIs) with response rates reported from 27-100%." (PMID 24423144, 2014). "Inhibition of autophagy increased the sensitivity of lung cancer cells to EGFR inhibitors, suggesting a novel approach to enhance targeted therapy of lung cancer." (PMID 25327881, 2014). "A common germline deletion in the BIM gene was recently shown to favor the production of non-apoptotic BIM isoforms, and to predict inferior responses in TKI-treated chronic myeloid leukemia (CML) and EGFR-driven lung cancer patients." (PMID 25090024, 2014). "As expected, EGFR expression was found to be positively correlated with CUL4A level in lung cancer tissues." (PMID 25413624, 2014).
lung cancer (continued). "Erlotinib, an inhibitor of EGFR enhances ATO mediated DNA double –strand break/damage by preventing EGFR –mediated DNA double-strand break repair human A549 lung cancer cells." (PMID 24887205, 2014). "Gefitinib and erlotinib are EGFR-tyrosine kinase inhibitors (TKIs) that have been approved for lung cancer treatment." (PMID 25009665, 2014). "EGFR mutation positivity is a good prognostic marker and patients with EGFR mutant lung cancer tend to have a longer survival." (PMID 25548673, 2014). "For example, gefitinib (Iressa), a selective EGFR tyrosine kinase inhibitor, is used for the treatment of lung cancer." (PMID 25236161, 2014). "Gefitinib was initially developed because improper activation of EGFR signaling appears frequently in lung cancer." (PMID 24658031, 2014). "Mutations in EGFR, resulting in greater affinity for ATP binding by the EGFR tyrosine kinase domain and constitutive activation, are found in ~15% of lung cancers in Caucasians and 40% in Asians." (PMID 25505733, 2014). "As already mentioned, ZEB1 was similarly shown to abrogate latent EGFR-induced senescence in lung carcinoma cells." (PMID 25566496, 2014). "In support of this assumption, ZEB proteins were indeed reported to protect lung cancer cells from EGFR-induced senescence through their ability to down-modulate CDKN1A and CDKN2B." (PMID 25566496, 2014). "The clinical efficacy of anti-EGFR therapy has been confirmed for a growing number of cancer types, including breast, colon, pancreas, head and neck, renal and lung carcinomas." (PMID 24801752, 2014). "We suggest the introduction of EGFR and KRAS mutation status analysis in the purpose of personalized lung carcinoma therapy of ILADC." (PMID 24782938, 2014). "An interaction of this phosphorylation site with the EGFR has been described, supporting it as a promising therapeutical target in breast and lung cancer." (PMID 23449029, 2013). "Many studies recently reported that HGF induced resistance to reversible EGFT-TKIs in EGFR mutant lung cancer cells by activating Met and the downstream phosphoinositide 3-kinase (PI3K)/Akt pathway." (PMID 23533466, 2013). "In the present study, IGFBP-3 expression was examined in EGFR mutant lung cancer cells with acquired resistance to EGFR-TKIs, and the value of serum IGFBP-3 level was evaluated as a marker of resistance." (PMID 24339922, 2013). "The relationship between tyrosine kinase receptors is so close that some lung cancer cell lines exhibited both EGFR and c-Met inhibition after gefitinib treatment." (PMID 23631593, 2013). "Cleavage of DSG2 was mediated by junction opener 1 (JO-1), and downstream signaling combined with a monoclonal antibody targeting EGFR, Erbitux, provide better therapeutic outcomes in EGFR-positive lung cancer." (PMID 24369726, 2013). "This was further supported by our observation that Mig6/EGFR demonstrated a high degree of accuracy as the predictor of EGFR activity in a large panel of head and neck, bladder and lung cancer cell lines examined." (PMID 23935914, 2013). "The concentrations of HGF in peripheral blood were found to be inversely correlated with clinical responses to EGFR-TKIs in both EGFR mutant and wild-type lung cancer." (PMID 23533466, 2013). "Here, we investigated IGFBP-3 expression in two EGFR mutant lung cancer cell lines with resistance to EGFR-TKIs and examined the value of serum IGFBP-3 level as a marker of resistance." (PMID 24339922, 2013). "The approach was to identify lung cancer cell lines with constitutively activated EGFR and use systematic selection of inhibitors to evaluate their effects on specific EGFR phosphorylations and downstream signaling pathways." (PMID 23866081, 2013). "The A549 tumor-cell line with wild-type EGFR, derived from a human alveolar epithelial cell carcinoma, has been studied in vitro to evaluate lung cancer behavior." (PMID 23232551, 2013).
lung cancer (continued). "Certain studies conducted in ovarian and lung cancer cell lines showed that the CXCR1/2 receptor/ligand pathway transactivates EGFR, promoting the downstream activation of MAPK signaling and mediating cell proliferation and survival." (PMID 23420470, 2013). "Hyperactivation of Epidermal Growth Factor Receptor (EGFR) tyrosine kinase is prevalent in human lung cancer and its inhibition by the tyrosine kinase inhibitors (TKIs), including gefitinib and erlotinib, initially controls tumor growth." (PMID 24280348, 2013). "This indicates that HGF is an ideal target for overcoming EGFR-TKI resistance in EGFR mutant lung cancer patients." (PMID 23690929, 2013). "The epidermal growth factor receptor (EGFR) is considered to be an important molecular target in lung cancer therapy." (PMID 23940741, 2013). "In recent years, targeted drug treatment has become a highlight for lung cancer, especially with the use of epidermal growth factor receptor-tyrosine kinase inhibitors (EGFR-TKIs)." (PMID 24351833, 2013). "The epidermal growth factor receptor (EGFR), which is up-regulated in lung cancer, involves the activation of mitogenic signals and triggers multiple signaling cascades." (PMID 23520446, 2013). "Further clinical development of this class of inhibitors in EGFR-mutant lung cancer patients who become refractory to reversible EGFR-TKIs is warranted." (PMID 24386407, 2013). "Resistance to epidermal growth factor receptor tyrosine kinase inhibitors (EGFR-TKIs), gefitinib and erlotinib, is a critical problem in the treatment of EGFR mutant lung cancer." (PMID 23690929, 2013). "EGFR is expressed in a variety of human tumors, including nonsmall cell lung cancer (NSCLC), breast, prostate, colorectal, bladder, and renal tumors." (PMID 23841084, 2013). "HGF, the sole ligand of Met, is important in the development of EGFR-TKI resistance in EGFR mutant lung cancer cells." (PMID 24386407, 2013). "For example, compounds were identified that attacked specific proteins displaying vulnerability for EGFR-mutant cells (CD11A/B) yet also have effects on proteins (CDK9) that have generalized anti-tumor effects across lung cancer cell lines." (PMID 24189400, 2013). "Our previous study using purified SH2 domains to characterize phosphotyrosine signaling in lung cancer cells found PC9 clustering among other EGFR-mutant cells." (PMID 24189400, 2013). "Mutant EGFR pulldowns identified MAPK adaptors GRB2 and SHC1 as well as ERRFI and UBS3B tyrosine phosphatase, all consistent with our results described in the lung cancer cell lines harboring mutant EGFR." (PMID 24189400, 2013). "For anti-EGFR therapy prediction, we demonstrate reliable in situ detection of KRAS mutations in codon 12 and 13 in colon and lung cancers in three different types of routinely processed tissue materials." (PMID 24280411, 2013). "Here, we used 14 different EGFR phosphorylation-site-targeted antibodies with in situ PLA to elucidate differences between EGFR-WT and EGFR-L858R mutant in lung cancer cells." (PMID 23520446, 2013). "As shown in various studies miRNA can modulate the response of lung cancer cells to EGFR TKIs by interacting with the respective signaling pathway." (PMID 23802096, 2013). "Unexpectedly, these two drugs both target EGFR, concurring that treating lung cancer patients using EGFR inhibitors is a feasible approach." (PMID 24369726, 2013). "The EGFR/KRAS mutations and the EML4-ALK translocation are called driver mutations because they are responsible for both the initiation and maintenance of lung cancer." (PMID 23341890, 2013). "We, thus, need to demonstrate the precise mechanisms by which bufalin overcame HGF-triggered resistance to apoptosis in EGFR-mutant lung cancer." (PMID 23533466, 2013).